TTR (transthyretin)
Diseases named in the same sentence as TTR in open-access papers (continued):
Sharing a sentence is not in itself a finding about the gene and the disease.
cardiac amyloidosis (continued). "Management is focused on stabilizing the transthyretin fibrils in the myocardium, in addition to the guideline-directed medical therapy (GDMT) for heart failure, to prevent the worsening deleterious outcome of untreated transthyretin cardiac amyloidosis." (PMID 40134993, 2025). "Most cardiac amyloidosis seen in the clinic is due to either amyloid light-chain (AL) of immunoglobulins or transthyretin accumulation in various cardiac structures." (PMID 40453263, 2025). "Transthyretin cardiac amyloidosis, secondary to the deposition of these amyloid fibrils, is characterized by reduced compliance of the heart and an increased risk of heart failure and death." (PMID 39043640, 2024). "Transthyretin (ATTR) and systemic light chain (AL) amyloidosis are the most common forms in general, as well as in the subtype of cardiac amyloidosis (CA)." (PMID 38592299, 2024). "Increased diagnostic awareness and specific disease treatments have changed the landscape of transthyretin cardiac amyloidosis (ATTR)." (PMID 39247984, 2024). "Of note, a recent systematic literature review on the screening and diagnosis of wild-type transthyretin amyloid cardiomyopathy found that the most frequently mentioned suspicion criteria were ventricular wall thickening." (PMID 39516862, 2024). "Cardiac amyloidosis (CA), either triggered by light chain (AL) or transthyretin (TTR) deposition in the heart, results in a restrictive relaxation pattern and heart failure (HF) with reduced prognosis." (PMID 38635117, 2024). "In cardiac amyloidosis (CA) there is an expansion of the intercellular space due to deposition of amyloid fibrils, mainly Transthyretin (ATTR) or immunoglobulin-derived light chains (AL), which lead to pseudo-hypertrophy of the myocardium." (PMID 38392254, 2024). "Cardiac amyloidosis, marked by transthyretin or immunoglobulin light-chain deposits, is increasingly recognized as a crucial contributor to heart failure." (PMID 38892799, 2024). "Wild-type transthyretin amyloid cardiomyopathy is an age-related, life-threatening disease resulting from the myocardial deposition of misfolded wild-type transthyretin." (PMID 38233673, 2024). "In November 2020, the patient was evaluated by hematology-oncology, and a fat-pad biopsy with Congo-red staining confirmed transthyretin cardiac amyloidosis." (PMID 39070422, 2024). "The treatment for TTR-related cardiac amyloidosis usually involves slowing fibril production and deposition, including gene silencing, TTR stabilization, and the destruction and re-absorption of amyloid deposits." (PMID 39199169, 2024). "When cardiac amyloidosis accumulation is detected, immunohistochemical subtyping is performed with Amyloid A, C4d, Fibrinogen, Pre Albumin/Transthyretin (TTR), Lambda, Lysozyme, and Kappa." (PMID 38111336, 2024). "Two main types of proteins identified in cardiac amyloidosis are light-chain amyloid and transthyretin amyloid." (PMID 39036123, 2024). "Though the role of transthyretin (TTR) in the development of cardiac amyloidosis has been recognized, the determinants of TTR levels remain unexplored." (PMID 39043640, 2024). "Another study from THAOS analyzed the TTR Val122Ile carriers with cardiac amyloidosis in the USA and also found increased male prevalence (75.8%)." (PMID 38907862, 2024). "The absence of myocardial uptake on Tc-99m pyrophosphate scintigraphy excluded transthyretin cardiac amyloidosis, further solidifying the diagnosis." (PMID 40078628, 2024). "In the context of cardiac amyloidosis, Tafamidis binds selectively to the thyroxine-binding sites of TTR tetramers, enhancing their stability." (PMID 38985360, 2024). "While the prevalence of transthyretin-derived amyloid cardiomyopathy (ATTR-CM) is on the rise, detailed understanding of its morphological and functional characteristics within the left ventricle (LV) across heart failure (HF) remains limited." (PMID 39286751, 2024).
cardiac amyloidosis (continued). "Cardiac amyloidosis can be grouped into two main categories: immunoglobulin light chain (AL) and transthyretin (hATTR or hereditary and ATTRwt or wild type)." (PMID 38800288, 2024). "Our prior study and a recent study investigated myocardial ischemia in a cohort of patients with cardiac amyloidosis (including AL and transthyretin, ATTR, cardiac amyloidosis) and control patients." (PMID 38873265, 2024). "Five out of 12 siblings developed progressive cardiac failure in their 40s due to a prominent TTR amyloid cardiomyopathy, which was clinically well‐documented." (PMID 38380705, 2024). "Transthyretin amyloid cardiomyopathy (ATTR-CM) is a subtype in which a protein known as transthyretin accumulates within the heart tissue, progressively resulting in restrictive cardiomyopathy and heart failure." (PMID 38985360, 2024). "Considering the centrality of TTR instability in the pathogenesis of cardiac amyloidosis, TTR levels have been used as a therapeutic target to evaluate the efficacy of disease-modifying therapy for TTR cardiac amyloidosis." (PMID 39043640, 2024). "In contrast, TTR-related cardiac amyloidosis is mostly a disease of individuals over 60–65 years of age." (PMID 38984491, 2024). "The rise in clinical awareness of transthyretin cardiac amyloidosis, along with the widespread use of sensitive imaging techniques, has led to an increase in the amount of diagnosis during the last years." (PMID 39274353, 2024). "We present a case of wild-type transthyretin cardiac amyloidosis incidentally discovered during two-vessel coronary artery bypass grafting (CABG) conducted for the resolution of diastolic congestive heart failure (CHF)." (PMID 38826962, 2024). "There are two types of cardiac amyloidosis: the more prevalent one related to immunoglobulin light-chain-derived (AL) amyloids and the other to transthyretin (ATTR) amyloids." (PMID 39202304, 2024). "Our third example, the ATTRibute-CM trial, randomized 632 patients with transthyretin amyloid cardiomyopathy in a 2:1 ratio to acoramidis hydrochloride or placebo." (PMID 39405050, 2024). "Two main types of proteins identified in cardiac amyloidosis are light-chain amyloid (AL) and transthyretin amyloid (ATTR)." (PMID 39036123, 2024). "Withdrawal: McGirr, K., Sarkar, S., Subramanian, K. (2023) "Quantitative modeling of approved and emerging therapeutics for modifying TTR levels in patients with Transthyretin Amyloid Cardiomyopathy" CPT: Pharmacometrics & Systems Pharmacology." (PMID 37932917, 2024). "Cardiac amyloidosis, encompassing both transthyretin (ATTR) and light-chain (AL) types, poses considerable challenges in patient management due to its intricate pathophysiology and progressive course." (PMID 39685743, 2024). "While cardiac amyloidosis is the primary Val122Ile outcome, our finding is consistent with previous reports supporting that Val122Ile may be related to peripheral neuropathy symptoms that are more often reported with respect to other TTR amyloidogenic mutations." (PMID 38523305, 2024). "Wild-type transthyretin cardiac amyloidosis (ATTRwt-CM) is an under-recognized aetiology of heart failure (HF), necessitating early detection for timely treatment." (PMID 39288026, 2024). "In evaluating tafamidis vs. placebo in 441 patients with transthyretin amyloid cardiomyopathy, the primary hierarchical composites were time to death and number of CV hospitalizations." (PMID 39405050, 2024). "Wild-type ATTR-CA (ATTRwt-CA), also known as age-related or senile cardiac amyloidosis, is characterized by misfolding of the theoretically normal wild-type transthyretin protein leading to amyloid deposition." (PMID 38826962, 2024). "Cardiac amyloidosis (CA) is an infiltrative cardiomyopathy divided into two types: light-chain (LA) and transthyretin (ATTR) CA." (PMID 38786346, 2024).
cardiac amyloidosis (continued). "Among them, diagnosed cardiac amyloidosis (CA) usually derives from the accumulation of amyloid fibrils made up of monoclonal immunoglobulin light chain (AL-CM) or transthyretin proteins (ATTR-CM)." (PMID 39274353, 2024). "Cardiac amyloidosis is a cardiomyopathy resulting from the extracellular deposition of proteins such as transthyretin (TTR)." (PMID 39157068, 2024). "While there are over 35 protein precursors that can contribute to amyloid deposits, most cases of cardiac amyloidosis are attributed to immunoglobulin light chains (AL amyloidosis) or transthyretin (ATTR amyloidosis)." (PMID 39687736, 2024). "In 2018, the randomized placebo-controlled, double-blind tafamidis in transthyretin amyloid cardiomyopathy clinical trial (ATTR-ACT) demonstrated that tafamidis was effective in treating patients with ATTR-CM with NYHA functional class I to III." (PMID 38233673, 2024). "The two main types of amyloid cardiomyopathy are amyloid light-chain amyloidosis and transthyretin (TTR) amyloidosis (ATTR)." (PMID 37416484, 2023). "While it can affect individuals of any ethnic background, there is growing evidence that people of African descent are disproportionately affected by cardiac amyloidosis, particularly transthyretin cardiac amyloidosis (TTR-CA)." (PMID 39681929, 2023). "Cardiac amyloidosis can be attributed to mutations found in TTR protein resulting in decreased stability and transthyretin (ATTR) misfolding." (PMID 37720240, 2023). "Although there are more than 30 identified amyloidogenic proteins, almost all cases of cardiac amyloidosis derive from aggregated transthyretin (TTR) or immunoglobulin light-chains." (PMID 37111614, 2023). "Most occurrences of cardiac amyloidosis result from two forms of precursor protein: transthyretin [TTR] amyloid and immunoglobulin-derived light-chain amyloid." (PMID 37720240, 2023). "Transthyretin (ATTR) cardiac amyloidosis has recently received increased attention; however, the diagnosis is often delayed." (PMID 37667698, 2023). "Patients with wild-type transthyretin amyloid cardiomyopathy (wtATTR-CM) typically present with symptoms of heart failure often associated with peripheral oedema, conduction disturbances and frequently, with a preceding history of atrial arrhythmia." (PMID 37653443, 2023). "On total body scintigraphy with Technetium-99m oxidronate, radiotracer deposit in the LV was greater than bone intensity, confirming the suspicion of transthyretin (TTR) amyloid cardiomyopathy." (PMID 37711552, 2023). "With the advent of novel therapies for transthyretin cardiac amyloidosis, the identification of pertinent prognostic strategies with the most accurate ability to detect increased adverse event risk in patients is an important research pursuit." (PMID 37297878, 2023). "Cardiac amyloidosis, characterized by extracellular amyloid fibrils in the heart, is predominantly seen in men, who make up 90% of patients with wild-type transthyretin cardiac amyloidosis (ATTRwt)." (PMID 37504533, 2023). "When affecting the heart, amyloid TTR protein fibrils can lead to transthyretin amyloid cardiomyopathy (ATTR-CM)." (PMID 37926810, 2023). "CA has two major subtypes, namely, transthyretin cardiac amyloidosis (ATTR) and light-chain amyloidosis." (PMID 37829941, 2023). "Recent studies have reported atrial involvement and coexistence of aortic stenosis in transthyretin (ATTR) cardiac amyloidosis (CA)." (PMID 37264308, 2023). "Cardiac amyloidosis (CA) is an infiltrative disorder which involves the myocardial deposition of misfolded proteins – with transthyretin (ATTR) CA as the most common CA subtype identified in elderly AS patients." (PMID 36877090, 2023). "Addressing the uneven burden of cardiac amyloidosis, specifically TTR-CA, in communities of African descent requires a comprehensive and multidimensional approach." (PMID 39681929, 2023).
cardiac amyloidosis (continued). "Along with transthyretin (TTR), myocardial infiltration by immunoglobulin light chains is the major cause of cardiac amyloidosis." (PMID 36899835, 2023). "In postmortem studies, cardiac amyloidosis (CA), especially “wild-type transthyretin” (ATTRwt), has shown a prevalence rate ranging from 22% to 25% in people older than 80 years, with a predominance for male patients." (PMID 36998972, 2023). "Transthyretin (TTR) amyloid cardiomyopathy (ATTR-CM) is a progressive and increasingly recognized cause of heart failure which is associated with high mortality and morbidity." (PMID 37111614, 2023). "Transthyretin (ATTR) cardiac amyloidosis (CA) is an infiltrative cardiomyopathy defined by myocardial deposition of insoluble amyloid fibrils." (PMID 36598681, 2023). "Cardiac amyloidosis (CA) is an uncommon, progressive, and fatal disease; the two main forms that can affect the heart are transthyretin CA and light chain CA (AL-CA)." (PMID 37338717, 2023). "This condition is categorized into two subtypes: transthyretin cardiac amyloidosis (ATTR-CA) and immunoglobulin light chain cardiac amyloidosis (AL-CA)." (PMID 37189662, 2023). "All subjects in this group were affected by transthyretin amyloid cardiomyopathy, with 50% reporting polyneuropathy and 38.8% reporting gastrointestinal disturbances." (PMID 38288300, 2023). "The patient was investigated to search for embolic sources in the suspect of recurrent paroxysmal AF, ischemic heart disease or cardiomyopathy, including metabolic disorders, and either wild-type or mutant transthyretin cardiac amyloidosis." (PMID 37711552, 2023). "Cardiac amyloidosis, specifically transthyretin cardiac amyloidosis (TTR-CA), poses a significant health burden in communities of African descent." (PMID 39681929, 2023). "Cardiac amyloidosis (CA) is characterized by extracellular infiltration and deposition of amyloid fibrils primarily derived from the circulating transthyretin protein (TTR) or immunoglobulin light chain (AL)." (PMID 36290299, 2022). "In this review, we provide an overview of current and experimental treatments for the predominant types of CA: transthyretin cardiac amyloidosis (ATTR-CA) and immunoglobulin light chain (AL)-mediated CA (AL-CA)." (PMID 35414852, 2022). "While more than 30 proteins can form the amyloid fibrils responsible for cardiac amyloidosis, monoclonal immunoglobulin light‐chain amyloid (AL) and transthyretin amyloid (ATTR) are the two main amyloid types that infiltrate the heart." (PMID 35795903, 2022). "Contractile reserve assessed by right ventricular free wall longitudinal strain is a predictor of major events in patients with wild-type transthyretin cardiac amyloidosis." (PMID 35440973, 2022). "TTR triggers amyloid processes, and TTR amyloid cardiomyopathy is increasingly being recognized in the clinical setting as a possible heart failure origin." (PMID 35216460, 2022). "The efficacy of diflunisal in cardiac amyloidosis due to mutant or wild-type TTR has been analyzed in several studies." (PMID 35497887, 2022). "Cardiac amyloidosis (CA) is an infiltrative cardiomyopathy resulting from deposition of misfolded immunoglobulin light chains (AL-CA) or transthyretin (ATTR-CA) proteins in the myocardium." (PMID 35402557, 2022). "In TTR-related cardiac amyloidosis, both prefibrillar, monomeric, and oligomeric species, exert direct proteotoxicity, and space-occupying amyloid fibrils, resulting in cardiac stiffness, cause heart dysfunction." (PMID 36555787, 2022). "Another recent study of patients with hereditary transthyretin (TTR) cardiac amyloidosis with polyneuropathy showed that administration of NTLA-2001 led to a decrease in serum TTR protein concentrations through targeted knockout of TTR." (PMID 35207566, 2022).
cardiac amyloidosis (continued). "A reduced average S’ (< 6 cm/sec) has been proposed as a highly accurate marker (Sensitivity 100%, Specificity 57%) to screen TAVI candidates for transthyretin cardiac amyloidosis, outperforming speckle-strain imaging parameters." (PMID 35006473, 2022). "The most common etiologies of cardiac amyloidosis (CA) are immunoglobulin light chain deposits (AL-CA) and misfolded transthyretin deposits (ATTR-CA)." (PMID 35328180, 2022). "For example, the advent of tafamidis for TTR amyloid cardiomyopathy represents a triumph of mechanism-based rational drug design." (PMID 37123434, 2022). "Amongst these proteins, TTR—in both hereditary and acquired forms—is the main protein involved in cardiac amyloidosis." (PMID 35897655, 2022). "The sample size of our cohort is small that is mainly explained by the fact that transthyretin cardiac amyloidosis remains a rare disease even in expert centers evaluating cardiopulmonary function in these patients." (PMID 36338485, 2022). "Cardiac scintigraphy with Tc99m-bone-avid radiotracers (PYP, HMDP or DPD) is highly specific in detecting transthyretin cardiac amyloidosis (ATTR-CA)." (PMID 35160323, 2022). "Studies on hip and knee arthroplasty related to cardiac amyloidosis have indicated the presence of TTR and light-chain amyloid in hip and knee synovium." (PMID 33419417, 2021). "Cardiac amyloidosis (CA) is an infiltrative disease characterised by accumulation of amyloid deposits in the extracellular space of the myocardium—comprising transthyretin (ATTR) and light chain (AL) amyloidosis as the most frequent subtypes." (PMID 33170349, 2021). "Here, we report a case of transthyretin cardiac amyloidosis and discuss the importance of imaging in establishing the diagnosis." (PMID 34262806, 2021). "Wild-type transthyretin cardiac amyloidosis (ATTRwt-CA, also referred to as senile cardiac amyloidosis) is frequently encountered in older adults." (PMID 34362197, 2021). "The frame-based accuracy and AUC obtained by the CNN classification of AL vs. TTR cardiac amyloidosis were 0.662 and 0.703 [0.664–0.741]." (PMID 35054236, 2021). "The current approach to TTR V142I identification typically relies on the presence of cardiac amyloidosis in a symptomatic individual." (PMID 33467513, 2021). "On the contrary, patients with cardiac amyloidosis transthyretin (ATTR) present with positive Tc-99m PYP scanning (intensive heart uptake)." (PMID 33907108, 2021). "Two types of precursor protein are responsible for most cardiac amyloidosis cases: transthyretin amyloid, and immunoglobulin‐derived light chain amyloid." (PMID 33595871, 2021). "Technetium-99m-labelled 3,3-diphosphono-1,2-propanodicarboxylic acid (99mTc-DPD scintigraphy) is recognized as highly accurate for the non-invasive diagnosis of transthyretin (ATTR) cardiac amyloidosis (CA)." (PMID 34254119, 2021). "The performance of AI integrating such multiparametric CMR features, especially for the distinction between AL and TTR cardiac amyloidosis, should be explored in the future." (PMID 35054236, 2021). "In elderly patients, as with this study, cardiac amyloidosis most often results from abnormalities in the liver protein transthyretin (TTR), a thyroxine and retinol-retinol binding complex transporter in blood." (PMID 34040908, 2021). "Cardiac amyloidosis is characterized by protein misfolding and myocardial deposition mainly of monoclonal light chain (AL) or transthyretin (ATTR), resulting in restrictive cardiomyopathy and heart failure." (PMID 34487268, 2021). "Transthyretin cardiac amyloidosis is characterized by extracellular insoluble transthyretin amyloid deposition." (PMID 34299270, 2021). "Here we show that a random forest machine learning model can identify potential wild-type transthyretin amyloid cardiomyopathy using medical claims data." (PMID 33976166, 2021).